RNU6-777P (RNA, U6 small nuclear 777, pseudogene)
Gene: Small nuclear RNA gene on chromosome 1 (12,077,881 to 12,077,984, reverse strand). Ensembl gene ENSG00000201135.
Homologues: Orthologues: chimpanzee U6 (98% identical), macaque U6 (88% identical), guinea pig U6 (87% identical), rat U6 (84% identical). Paralogues in human: RNU6-11P (88% identical), RNU6-37P (88% identical), RNU6-38P (87% identical), RNU6-1 (86% identical), RNU6-2 (86% identical), RNU6-28P (86% identical), RNU6-3P (86% identical), RNU6-4P (86% identical), RNU6-5P (86% identical), RNU6-6P (86% identical), RNU6-7 (86% identical), RNU6-8 (86% identical), and 1286 more.